HPSE (heparanase)
Diseases named in the same sentence as HPSE in open-access papers (continued):
Sharing a sentence is not in itself a finding about the gene and the disease.
lymphoma (17 papers, 2008 to 2025). A malignant (clonal) proliferation of B- lymphocytes or T- lymphocytes which involves the lymph nodes, bone marrow and/or extranodal sites. "The analysis revealed a statistically increased HPSE expression in bladder, brain, CNS, breast, gastric, leukemia, lung, lymphoma, and sarcoma tumors compared to matched normal tissues." (PMID 34461608, 2021). "Another approach was utilizing heparanase-neutralizing monoclonal antibodies that strongly attenuate lymphoma cell tumor load in mouse bones due to tumor cell growth inhibition and reduced angiogenesis." (PMID 33800172, 2021). "The monoclonal antibodies 9E8 and H1023 neutralize heparanase enzymatic activity and prevent spontaneous hepatic metastasis of ESb lymphoma cells from the primary tumor." (PMID 35118073, 2021). "Consistent with this, PG545 was recently reported to have apoptotic effects on lymphoma cell lines that lack heparanase expression." (PMID 32117279, 2020). "Curiously PG545 has been found to elicit autophagy and persistent ER stress in lymphoma cells, which triggered their apoptosis, and this occurred independently of heparanase." (PMID 31850210, 2019). "We have previously noted that over expression of heparanase enhances the adhesion of mouse Eb lymphoma cells to ECM and endothelial cells." (PMID 18545691, 2008). "Moreover, neutralizing anti-heparanase monoclonal antibodies were reported to attenuate lymphoma and myeloma tumor growth in mouse models, but were never examined in patients." (PMID 40940793, 2025). "Similarly, the same conclusion was made for lymphoma cells: by solubilizing the glycosaminoglycan (GAG) scaffolding of the sub-endothelial ECM, heparanase-1 facilitates the spread and extravasation of metastatic T lymphoma cells through the blood vessel walls." (PMID 36680276, 2023). "Moreover, PG545 was shown to exert anti-tumor effects discrete from heparanase inhibition as it induces lymphoma cell apoptosis in a non-heparanase-dependent manner." (PMID 33800172, 2021). "Both mAbs inhibited lymphoma growth in xenogeneic murine models via a mechanism that did not involve a direct cytotoxic effect on the tumor cells, but rather seemed to be a result of neutralization of heparanase activity in the tumor microenvironment." (PMID 31850210, 2019). "PG545 did not affect naïve splenocytes but induced apoptosis even in lymphoma cells deployed of heparanase activity." (PMID 33800172, 2021). "In addition, T lymphoma cells transfected with the heparanase gene saw a considerable increase in neovascularization near implanted tumors when compared to the nontransfected T lymphoma cells." (PMID 20445741, 2010). "Indeed, a recent study has highlighted that inhibitors of heparanase—an enzyme that modulates the ECM and promotes both a tumor-permissive microenvironment and autophagy activation—show early signs of efficacy in lymphoma, althought its role in GBM remains unknown." (PMID 40813676, 2025). "Indeed, a study showed the effect of heparanase-neutralizing antibodies to attenuate the growth of lymphoma cells that do not express heparanase, implying that targeting microenvironment may be sufficient." (PMID 31963505, 2020).
breast tumor (14 papers, 2010 to 2022). "Heparanase enzyme is preferentially expressed in obesity-associated breast tumors in clinical/experimental settings and associated with worse prognosis in ER+, but not ER− BC." (PMID 36139419, 2022). "They provided evidence that heparanase preferently is expressed in clinical/experimental obesity-associated breast tumors, and that heparanase deficiency abolishes obesity-accelerated orthotopic tumor growth." (PMID 33987528, 2021). "In this study, we found that elevated heparanase expression is associated with an increased risk of recurrence in ER+ breast tumors." (PMID 34050190, 2021). "Heparanase was significantly associated with worse prognosis in the general population (p < 0.01−10) and in each breast tumor subtypes separately." (PMID 34050190, 2021). "On the other hand, in vitro treatment with recombinant heparanase enzyme prior to stimulation by SFA (mimicking overexpression of the enzyme in obesity-associated breast tumors) resulted in a 4-fold increased ability of SFA-stimulated Mφ to upregulate ERα expression in E0771 and MCF7 cells." (PMID 36139419, 2022). "This analysis demonstrated, that heparanase is associated with worse outcomes in breast tumors." (PMID 34050190, 2021). "Heparanase enzyme has also been implicated in breast tumor progression." (PMID 28038446, 2017). "Furthermore, we found that in ER+ breast tumors the risk of disease recurrence following chemotherapy, but not hormone therapy, for patients with increased heparanase expression was greater than for patients with low heparanase expression." (PMID 34050190, 2021). "Of note, although heparanase is expressed by both Mφ and BC cells numerous observations have repeatedly indicated that in the setting of breast tumors, carcinoma cells per se appear to represent the major cellular source of the enzyme." (PMID 36139419, 2022). "We, therefore, evaluated the predictive role of heparanase on the benefit derived from chemotherapy or hormonal therapy in ER+ breast tumors." (PMID 34050190, 2021). "In the present study, we analysed the potential benefit of pre- and post-treatment heparanase concentration as a marker for breast tumour invasion, pro-angiogenic phenotype, treatment response, and prognosis." (PMID 34070058, 2021). "Our present study focuses specifically on the involvement of heparanase in chemoresistance of ER-positive (ER+) breast tumors." (PMID 34050190, 2021). "The authors have claimed that heparanase enhanced the blood and oxygen delivery of both the breast tumours and lung metastases through a new vessel network and vascular mimicry, thus leading to tumour growth and malignant progression." (PMID 34070058, 2021). "Breast tumor cells when co-cultured with lymphocytes from healthy donors were shown to induce heparanase expression by the lymphocytes." (PMID 31110966, 2019). "The MMTV-heparanase mice promoted growth and metastasis of breast tumor cells to lungs suggesting a role for heparanase in BC progression." (PMID 29983921, 2018). "In the present study, GYII attenuated heparanase expression and angiogenesis in murine primary breast tumors." (PMID 28505136, 2017). "Furthermore, these experiments suggested that the breast tumor cells induced the lymphocytes to produce soluble factors that were responsible for upregulating heparanase expression." (PMID 31110966, 2019). "Yet, ER status could still be an important factor in inducing heparanase expression in breast tumors, therefore contributing to the occurrence of INSR-heparanase interplay under diabetic state." (PMID 28038446, 2017). "In agreement, heparanase enhances insulin-induced proliferation of breast tumor cells in vitro." (PMID 28038446, 2017). "Our results provide convincing evidence for cytosine methylation as a molecular mechanism involved in transcriptional regulation of heparanase gene expression and demonstrate that DNA methylation of heparanase do undergo distinct changes during breast tumor progression." (PMID 24632672, 2014).
breast tumor (continued). "Similarly, the heparanase are preferentially overexpressed in human breast tumors when compared with the normal counterpart." (PMID 24632672, 2014). "Thus, estrogen is expected to upregulate heparanase in breast tumor cells per se." (PMID 28038446, 2017). "In contrast, HPSE2, a homologue of HPSE that is able to interact with HS with high affinity, hence it being proposed to have anti-cancer properties, exhibited strong underexpression in all the patients studied, pointing to this gene having an important role in breast tumor progression." (PMID 23327652, 2013). "To further validate these results, we examined the expression levels of HPSE, HLA-F, and SELL in primary breast tumors with high CDYL2b expression." (PMID 32373210, 2020). "Worth mentioning is the fact that, similarly to obesity per se, expression of heparanase correlates with worse outcome in ER+, but not ER−, breast tumors." (PMID 36139419, 2022). "Immunohistochemical staining for heparanase was detected in all 4T1 breast tumor and lung tissue, as well as in lung tissue from non-tumor bearing mice." (PMID 23300607, 2012).
colon carcinoma (14 papers, 2008 to 2024). "This notion is supported by a study utilizing a mouse model of colitis-associated colon carcinoma, showing that heparanase promotes polarization of innate immunocytes toward pro-inflammatory and/or pro-tumorigenic phenotype." (PMID 34220822, 2021). "Taken together, our data suggest that HPSE overexpression is associated with changes in the resistance of colon cancer cells to chemo- and radio- therapy, involving a differential role for the enzymatic activity of HPSE." (PMID 32477959, 2020). "Our results report for the first time the dynamic interplay between Sdc-1 and HPSE in stemness-associated colon cancer via a signaling axis involving early growth response protein 1 (EGR1), FAK, and Wnt." (PMID 32477959, 2020). "To summarize, we have shown for the first time the involvement of HPSE in colon cancer stem cell properties and observed an increase in cell invasiveness linked to the regulatory interplay of Sdc-1 and HPSE." (PMID 32477959, 2020). "Based on the deregulated expression of Sdc-1 and HPSE in colon cancer and the role of Sdc-1 as a signaling co-receptor, we hypothesized that loss of Sdc-1 may regulate HPSE expression." (PMID 32477959, 2020). "siRNA-depletion of Syndecan-1, and upregulation of heparanase increased the colon cancer stem cell phenotype based on sphere formation assays and phenotypic marker analysis (Side-population, NANOG, KLF4, NOTCH, Wnt, and TCF4 expression)." (PMID 32477959, 2020). "In colon cancer pathogenesis, complex changes occur in the expression pattern of Syndecan-1 and heparanase during progression from well-differentiated to undifferentiated tumors." (PMID 32477959, 2020). "Here we investigated the regulatory and functional interplay of Syndecan-1 and heparanase employing siRNA-mediated silencing and plasmid-based overexpression approaches in the human colon cancer cell line Caco2." (PMID 32477959, 2020). "Research has shown that heparanase has important roles in relation to the progression of esophageal, stomach and colonic cancer." (PMID 25351637, 2015). "High expression of heparanase was found in primary colon cancer as well as in colon cancer metastases to the lungs, liver, and lymph nodes." (PMID 24887057, 2014). "Our findings could form a conceptual framework for establishing novel therapeutic possibilities and recognize the long-term driven functions of Sdc-1 and HPSE in colon cancer." (PMID 32477959, 2020). "Notably, a decrease in Sdc-1 and increase in HPSE expression has been observed in several cancers particularly in colon cancer enhancing tumorigenesis, invasion, and metastasis." (PMID 32477959, 2020).
endothelial dysfunction (14 papers, 2019 to 2025). In vascular diseases, endothelial dysfunction is a systemic pathological state of the endothelium (the inner lining of blood vessels) and can be broadly defined as an imbalance between vasodilating and vasoconstricting substances produced by (or acting on) the endothelium. "Heparanase specifically cleaves heparan sulfate fragments from the proteoglycan, resulting in a loss of integrity and, thus, in endothelial dysfunction." (PMID 36142913, 2022). "This induces heparanase expression and subsequent degradation of the endothelial glycocalyx and could explain the mechanisms underlying the development of endothelial dysfunction under such conditions." (PMID 35867189, 2022). "High SJL was also associated with increased endothelial dysfunction and higher PAI-1, heparanase level, heparanase procoagulant activity, and D-Dimer levels." (PMID 39859197, 2025). "Increased heparanase activity correlated with the endothelial dysfunction markers heparan sulfate and syndecan-1, as well as clinical markers of plasma leakage such as ascites, hematocrit concentration and gall-bladder wall thickening." (PMID 34987504, 2021). "Furthermore, UFH has been demonstrated to protect the endothelial glycocalyx via heparanase and ameliorate pulmonary microvascular endothelial dysfunction, which contributes to the improvement of microcirculation." (PMID 38167115, 2024). "Studies have found that inhibited heparanase activation could protect pulmonary endothelial glycocalyx integrity and reduce endothelial dysfunction." (PMID 35185540, 2021). "This study aimed to determine how heparanase from fatty tissue may contribute to endothelial dysfunction and inflammation in patients with hyperglycemia and in a hyperglycemia model in rats." (PMID 31890010, 2019). "Studies have found that inhibited heparanase activation could protect pulmonary endothelial glycocalyx integrity and reduce endothelial dysfunction, which indicated that inhibition of HPSE1 activity or upstream regulatory mechanisms might be helpful in inhibiting the vascular disease progression." (PMID 35185540, 2021). "HPSE expression is induced by both SARS-CoV-2 and MPXV in severely affected patients leading to induction release of pro-inflammatory cytokines, endothelial dysfunction, and coagulopathy." (PMID 36705773, 2023). "GAG binding and activation of enzymes like MMP9, HPSE, hyaluronidase, and neuraminidases are common requirements for both NS1- and S-mediated endothelial dysfunction." (PMID 36494335, 2022).
sarcoma (13 papers, 2011 to 2024). A usually aggressive malignant neoplasm of the soft tissue or bone. "Intense research efforts during the last two decades revealed that heparanase expression is upregulated in various human carcinomas, sarcomas, and hematological malignancies." (PMID 38334603, 2024). "Consistently with its tumor-supporting activity, heparanase expression is upregulated in carcinomas, sarcomas, and hematological malignancies." (PMID 35454809, 2022). "Heparanase is expressed in SS cell lines and tumor specimens and preclinical studies using HS mimetics and small molecule heparanase inhibitors have indicated heparanase and HSPGs as druggable targets in different types of sarcoma models including SS." (PMID 34857011, 2021). "The relationships between heparanase and poor prognosis have been demonstrated in various carcinomas, sarcomas, and hematologic malignancies." (PMID 34050190, 2021). "Heparanase has been shown to be an actionable target in various sarcoma models and we have reported that both heparin derivatives and small molecule heparanase inhibitors produce a remarkable impact on SS cell malignant behavior in vitro and in vivo." (PMID 34857011, 2021). "We previously demonstrated the antitumor effect of the glycol-split heparin derivative heparanase inhibitor roneparstat (SST0001) in a panel of pediatric sarcoma models including an ES, RMSs, and OSs." (PMID 27374103, 2016). "The study supports heparanase/HS axis targeting as a valuable approach in combination therapies of different sarcoma subtypes providing a preclinical rationale for clinical investigation." (PMID 27374103, 2016). "In summary, this study confirms interference with the heparanase/HS functions as a valuable antitumor approach in preclinical sarcoma models and a promising strategy to enhance efficacy in combination therapies." (PMID 27374103, 2016). "The heparan sulfate (HS) mimic/heparanase inhibitor roneparstat (SST0001) shows antitumor activity in preclinical sarcoma models." (PMID 27374103, 2016). "Heparanase has a central role in the development of various tumors, and its expression has been associated with increased tumor growth, angiogenesis and metastasis, but there is insufficient information about the function of heparanase in sarcomas." (PMID 24887057, 2014). "The current study is the first attempt to evaluate the level of heparanase over-expression in sarcoma that frequently occurs in adults, showing a similar percentage of over-expression as in children’s sarcoma subtypes." (PMID 24887057, 2014). "It is possible that, due to the high level of heterogeneity of the various histological types of sarcoma, a much larger sample group would be required to reveal the role of heparanase as a prognostic factor in sarcomas." (PMID 24887057, 2014). "Several lines of evidence indicate that heparanase is upregulated in all human sarcomas and carcinomas." (PMID 23984412, 2013). "Heparanase expression is upregulated in human carcinomas, sarcomas, and hematological malignancies, correlating with increased tumor metastasis, vascular density, and shorter postoperative survival of cancer patients, and encouraging the development of heparanase inhibitors as anti-cancer drugs." (PMID 38334603, 2024). "In light of the development of heparanase inhibitors as novel treatment options, it is important to carry out further studies, which should include larger patient groups with specific sub-type sarcomas, in order to better delineate the significance of heparanase in STS." (PMID 24887057, 2014). "The heparan sulfate chains of proteoglycans can be cleaved by heparanase, an enzyme endowed with endo-glucuronidase activity, which generates proteoglycan products that are highly active in promoting cancer progression and the dissemination of carcinomas, sarcomas, and hematological malignancies." (PMID 35454809, 2022).
sarcoma (continued). "In addition to heparanase, HS mimetics were found to target the cell signaling, supported by HSPGs, of receptor tyrosine kinases relevant in angiogenesis and in the pathobiology of various sarcoma subtypes." (PMID 34857011, 2021). "A potential relationship between deregulated heparanase/HSPG axis and oncogenic players in the different sarcoma subtypes remains to be elucidated." (PMID 34857011, 2021). "For example, SST0001, a modified heparin, significantly reduces in vivo heparanase activity and controls levels of growth factors including HGF and VEGF, thereby preventing angiogenesis in human pediatric sarcoma models." (PMID 35118073, 2021). "While the clinical significance of heparanase in human carcinomas is well documented and anti-heparanase compounds are being tested in clinical trials, the role of heparanase in mesenchymal tumors such as sarcoma has not been investigated in detail." (PMID 24887057, 2014).